DEFB109B (defensin beta 109B)
Description:
Has antibacterial activity.
Synonyms: DEFB-109; HBD9; DEFB109P1B; DEF109P1B; DEFB109
Tractability: Antibody: UniProt places it where antibodies can reach, with medium confidence; UniProt predicts a signal peptide or a membrane-spanning region; its Gene Ontology location is reachable by antibodies, with medium confidence.
Gene: Protein-coding gene on chromosome 8 (7,312,722 to 7,320,096, forward strand). Ensembl gene ENSG00000206034.
Subcellular location: Secreted
Pathways (Reactome):
Immune System: Beta defensins
Gene Ontology:
Molecular function: CCR6 chemokine receptor binding; chemoattractant activity
Biological process: cell chemotaxis; defense response to bacterium; positive chemotaxis
Cellular component: extracellular region
Homologues: Orthologues: dog DEFB109B (72% identical), rat Defb42 (64% identical), mouse Defb48 (60% identical). Paralogues in human: DEFB109C (100% identical), DEFB109D (91% identical), DEFB130A (39% identical), DEFB130B (39% identical), DEFB4A (21% identical), DEFB4B (21% identical).
Diseases named in the same sentence as DEFB109B in open-access papers:
DEFB109B is named in the same sentence as 1 disease in open-access papers, as found by Europe PMC text mining. Sharing a sentence is not in itself a finding about the gene and the disease.
DEFB109B shares sentences with these, for which no sentence is quoted: infectious keratitis (1 paper).